MMP1 (matrix metallopeptidase 1)
Diseases named in the same sentence as MMP1 in open-access papers (continued):
Sharing a sentence is not in itself a finding about the gene and the disease.
cancer (continued). "Previous studies have demonstrated that MMP1 enhances cancer invasion and metastasis while also regulating cancer stemness and chemoresistance." (PMID 40475780, 2025). "Our study identified the crucial role of MMP1 (matrix metalloproteinase 1) in the transition from normal pancreatic cells to cancer cells." (PMID 40092486, 2025). "This interaction holds the potential to induce alterations in cancer cell growth, mobility, and survival, offering a distinctive avenue compared to traditional pathways, such as those activated by MMP1." (PMID 40877222, 2025). "MMP1, a matrix metalloproteinase, promotes cancer progression by degrading the extracellular matrix." (PMID 40657637, 2025). "A subtype of CAFs characterized by high MMP1 expression exhibiting characteristics of both myCAFs and iCAFs was reported in a cross‐tissue scRNAseq analysis in different cancer types, including lung cancer." (PMID 40908670, 2025). "MMP1 has been found with elevated expression in series primary cancers and its prognostic value has been revealed in several cancers." (PMID 38320998, 2024). "We are now the first team to determine MMP-1 concentrations in OC patients, so our results will be partially applicable to other cancer types." (PMID 39682156, 2024). "In the search for more promising therapies, matrix metalloproteinases have become of significant interest, such as MMP-1, MMP-2, MMP-9, and MMP-13, which have been linked to more aggressive forms of cancer and earlier metastases." (PMID 39063046, 2024). "It is well established that MMP1 is a collagenase expressed by human stromal fibroblasts and cancer cells." (PMID 38891088, 2024). "These factors must activate MMP-1 only in response to inflammation, to avoid pathological outcomes such as cancer." (PMID 39154080, 2024). "We further measured the expression of MMP1 in cancer cell lines and primary NFs from HNSCC patients." (PMID 38320998, 2024). "Among them, MMP1 and MMP3 are known to be associated with cancer growth, invasion, and metastasis, and they were also increased in Huh7 cells after arsenite exposure." (PMID 39756915, 2024). "As a member of the peptidase M10 family of matrix metalloproteinases, MMP1 was proved to play key roles in a variety of cancers by remodeling the extracellular matrix." (PMID 38320998, 2024). "Matrix metalloproteinase-1 (MMP1) has an aberrant expression relevant to various behaviors of cancer." (PMID 38320998, 2024). "Matrix metalloproteinase-1 (MMP1) has an aberrant expression relevant to various behaviors of cancers." (PMID 38320998, 2024). "Recent studies suggest that MMP-1 promotes cancer cell invasion and migration and significantly correlates with malignancies’ unfavorable outcomes." (PMID 37513440, 2023). "Most MMPs have consistently increased gene expression across cancers, and MMP1, MMP9, MMP10, MMP11, and MMP13 are almost universally upregulated across a wide variety types of cancers." (PMID 36903626, 2023). "Matrix metalloproteinases (MMPs) are closely related to angiogenesis, invasion, metastasis, and the avoidance of immune surveillance in the course of cancer, among which MMP1 and MMP9 are universally upregulated in almost all cancers." (PMID 37202657, 2023). "Studies have reported the benefit of retinoids in preventing cancer invasion and metastasis by targeting proteases (MMP-1, MMP-2, MMP3, uPA) involved in the degradation of the extracellular matrix (ECM)." (PMID 38249515, 2023). "Transcriptome analysis revealed that CHRM3 knockdown significantly reduced an array of classic factors in cancer invasive growth including MMP1/MMP3/MMP10/MMP12 and CXCL1/CXCL5/CXCL8." (PMID 37744266, 2023). "Transcriptome analysis revealed that CHRM3 knockdown significantly reduced an array of classic factors involved in cancer invasive growth, including MMP1/MMP3/MMP10/MMP12 and CXCL1/CXCL5/CXCL8." (PMID 37744266, 2023).
cancer (continued). "Both MMP1 mRNA and protein are highly expressed in various cancers and play a vital role in initiating tumorigenesis by disrupting the stroma and releasing growth factors." (PMID 37151391, 2023). "Similar types of MMPs were found to be increased in both cancers, namely, MMP-1, MMP-2, MMP-9, and MMP-11." (PMID 36982551, 2023). "It has also been reported that cancer cells induce the secretion of MMPs, such as MMP-1, via the upregulation of ROS to enhance vascular growth in the cancer microenvironment." (PMID 37564184, 2023). "Our analysis identified several previously known carcinogenic L1 ASP-associated genes, such as MMP1 and GTSE1, which were up regulated in multiple cancer types." (PMID 37723560, 2023). "In various cancers, including ovarian cancer, FDFT1 is associated with invasion and activates cancer cell metastasis through MMP1, CD44, and AKT/mTOR/HIF1α signaling." (PMID 37107644, 2023). "MMP1 plays a key role in the proliferation and migration of cancer cells, as well as the angiogenesis of cancer." (PMID 36824434, 2023). "MMP1 is involved in the development of several cancers, and MMP1 upregulation promotes extracellular matrix degradation during the epithelial-mesenchymal transition and enhance migration and invasion of HCC cells." (PMID 37309005, 2023). "When HNSCC cell lines and CAFs were cocultured, MMP-1 expression was increased in both the cancer cells and the CAFs." (PMID 37055382, 2023). "As a crucial member of the MMP family, the aberrant expression of matrix metalloproteinase-1 (MMP1) has involved in various behaviors of cancer." (PMID 36105241, 2022). "Accumulating evidence suggested that MMP1 was highly expressed in most cancers as well as pan-cancer analysis from GEPIA2." (PMID 36105241, 2022). "High matrix metalloproteinase-1 (MMP1) expression was found that have a great graft advantage in xenografts and is associated with pooled disease-free survival in cancer patients." (PMID 35444950, 2022). "Patients with high percentage of cancer associated fibroblasts and expression of TIMP3 but low expression of COL1A1, COL3A1, MMP1 and POSTN were associated with sensitivity to paclitaxel." (PMID 35480306, 2022). "MMP1 expression level is increased in various malignant tumors and is correlated with poor prognosis." (PMID 35414794, 2022). "According to our findings, the GPX3 expression is markedly decreased in most cancers, while MMP1 and MMP12 expression was distinctly upregulated in most types of tumors." (PMID 36081670, 2022). "Salivary MMP-1 levels were found to increase significantly between stage I and stage IV patients, thus reflecting cancer progression." (PMID 36430813, 2022). "High expression of MMP1 was found in 30.7% of cancer tissues but 1.2% of pan-cancer tissues (P=0.00)." (PMID 35037689, 2022). "Matrix metalloproteinase-1 (MMP1) has been reported to play key roles in a variety of cancers by degrading the extracellular matrix." (PMID 36105241, 2022). "mmp1 promotes cell cycle acceleration in cancer cells by activating the cdc25a/CDK4-cyclin D1 and p21/cdc2-cyclin B1 complexes." (PMID 36225568, 2022). "The genes observed in this network (CEACAM1, IGF1, MET, MMP1, MMP3 and WNT5A) were upregulated in cSII/III and are known to be linked to invasive properties in several other cancer types." (PMID 35022523, 2022). "It has been shown that matrix metalloproteinase-1(MMP1) is related to poor prognosis in cancers such as BRCA, CESC and COAD." (PMID 36727076, 2022). "MMP1 is a classic gene that can act as an oncogene and accelerate the progression of most cancers including NSCLC." (PMID 35480306, 2022). "TCGA database showed that the expression of MMP1 in most cancer tissues was significantly higher than that in adjacent tissues." (PMID 35414794, 2022). "Taken together, these results indicate that MMP1 is a crucial oncogene to stimulate MCF-7 cancer cell growth and a driving factor for drug resistance." (PMID 35267540, 2022).
cancer (continued). "GSEA, GO, and KEGG analyses showed that MMP1 expression was significantly related to cancer-related pathways and cancer-related functions." (PMID 36105241, 2022). "MMP1 is a member of a family of zinc-dependent endopeptidases involved in wound healing, inflammation, cancer and angiogenic remodeling of the extracellular matrix (ECM)." (PMID 36225568, 2022). "We used TIDE, EPIC and MCPCOUNTER algorithms to analyze the correlation between immune cells infiltration and MMP1 expression in pan-cancer based on the TIMER2." (PMID 36727076, 2022). "The pan-cancer survival network further enriches the inhibition of matrix metalloproteases (A2M, MMP1, MMP14, MMP3, TIMP4)." (PMID 35106465, 2022). "CD147 has been shown to facilitate the secretion of extracellular matrix-degrading metalloproteases from fibroblasts, endometrial cells and cancer cells, such as MMP-1, MMP-3, MMP-9 and membrane type 1-MMP." (PMID 34997863, 2022). "Effects of matrix metalloproteinase-1 (MMP1) expression on cancer cell growth and drug resistance were examined through colony formation assays and flow cytometry." (PMID 35267540, 2022). "MMP1, is upregulated by the EBV proteins LMP1 and Zta and upregulation of MMP1 has been shown to confer the invasive properties of EBV associated cancers." (PMID 35698050, 2022). "PCA loadings show that the genes exerting the largest effects include MMP1 and MMP10, KRT7, and KRT19, high levels of which in other cancers have been associated with unfavorable prognosis." (PMID 35480116, 2022). "These genes are known to be regulated by MMP1 and their increased expression has been shown to promote proliferation and metastasis of cancer cells." (PMID 35267540, 2022). "In particular, nuclear MMP-3 can regulate connective tissue growth factor (CTGF) expression by interaction with the heterochromatin protein gamma, and CTGF increases the transcription of several MMPs, including MMP-1, -2, -3, and -9, in cancer cells." (PMID 36142454, 2022). "Using the cBioPortal, we conducted a comprehensive analysis of genetic alteration status of MMP1 across different cancers in the TCGA database." (PMID 35948625, 2022). "Several previous reports have proposed important clinical relevance of MMP1 overexpression in human cancer." (PMID 36105241, 2022). "The movement of cancer cells is facilitated by channels formed in the ECM that is regulated by MMP-1 activity." (PMID 35586209, 2022). "The exosome-activated mCAFs upregulate the activity of genes for MMP-1, MMP-2, MMP-7, MMP-8, MMP-13 and MMP-14 that are associated with cancer growth and progression." (PMID 34837514, 2022). "Strikingly, epithelial mesenchymal transition (EMT) as a predominant phenotype of cancer metastasis, were found to be significantly associated with NPC progression (FDR <0.0001) with MMP1 as the leading gene in the EMT gene set." (PMID 35433690, 2022). "MMP-1 is a zinc-dependent protease that degrades collagen and other extracellular matrix molecules and is a potential target in cancer therapy, indicating the great need to protect against IR radiation for future formulations." (PMID 35482661, 2022). "The WB result showed that MMP1 protein expressed much higher in cancer tissues than adjacent normal tissues." (PMID 35426219, 2022). "This is particularly true when considering the close interaction of STAT3 and NF-κB members in regulating both separately or together the expression of numerous genes (e.g., MMP-1) involved in cancer initiation, metastasis, and resistance to therapies." (PMID 36139106, 2022). "MMP1 as a critical member of the MMP family, a variety of evidence have reported its oncogenic roles and prognostic significance underlying multiple cancer contexts." (PMID 36105241, 2022). "The data suggested that MMP1 had a high accuracy (AUC > 0.9) in predicting the diagnosis in 15 cancer types." (PMID 36727076, 2022).
cancer (continued). "As for degree of differentiation, salivary MMP-1 levels in poorly differentiated (G3) cancers show a median difference of 4.5-fold when compared to those with undifferentiated and well-differentiated (G0-1) patients." (PMID 36430813, 2022). "MMP1 expression showed a significant increase in all cancer cells treated with each antiplatelet agent." (PMID 36076991, 2022). "MMP1 has been reported to act as a critical factor in accelerating cancer progression by upregulating the capacity of migration and invasion in cancer cells." (PMID 34445346, 2021). "The interest on this protein has grown because it was demonstrated that CD147 enhances the invasion and survival of cancer cells mediating the activity of MMP-1, MMP-2, MMP-3, MMP-9, and MMP-11." (PMID 34944575, 2021). "Evidence on flavonoids like curcumin and its derivatives reports the suppression of migratory activity in cancer cells by inhibition of MMP1." (PMID 33921173, 2021). "CD147 induces MMP-1, -2, -3, and -9 in cancer cells and neighboring stromal cells, resulting in the regulation of ECM remodeling during inflammatory response and wound healing." (PMID 34944575, 2021). "This study confirmed that MMP1 participated in collagen metabolism and the degradation of extracellular matrix tissue, promoting cancer metastasis." (PMID 35069702, 2021). "According to previous research, the high expression of MMP-1 in cancer is relevant, as it is particularly helpful during the invasion and metastasis of tumor cells." (PMID 35010011, 2021). "In the present study, we have developed MMP-1 antibody-conjugated iron–gold bimetallic NPs as a potential platform for hyperthermia-mediated cancer cellular death." (PMID 35010011, 2021). "Matrix metalloproteinase-1 (MMP-1), also known as collagenase-1, has been demonstrated to mediate the pathological progression of diverse cancers." (PMID 34590603, 2021). "The downregulated genes TNC and MMP1 are known to be commonly induced in cancer, the same is true for PMP2 and CDH2." (PMID 34439267, 2021). "Of note, etanercept demonstrated marked inhibition of genes involved in LPS-mediated tissue injury and possibly a role in the process of transformation of normal epithelial cells to cancer cells, such as MMP-1 and PTGS2." (PMID 34648530, 2021). "MMP1, a member of the zinc-dependent endopeptidase family, has been demonstrated to be closely relevant to migration and invasion in a number of cancers." (PMID 33391541, 2021). "The expression of MMPs (MMP-1,−2,−8 to−13,−15,−19,−23,−24,−27, and−28) is comparatively much stronger in cancer tissues than normal tissues of the breast." (PMID 33520928, 2020). "High expression of MMP1 in cancer tissues leads to accelerated angiogenesis, thus promoting the proliferation and migration of cancer cells." (PMID 33490103, 2020). "Among them, MMP1 has been proved to be highly expressed in various kinds of cancers, mainly acting to degrade type I and type III collagen in the extracellular environment." (PMID 32703314, 2020). "Our data further indicate that salivary MMP-1 levels in patients with undifferentiated and well-differentiated (G0-1), moderately differentiated (G2), and poorly differentiated (G3) cancers were 1150.3, 1273.2, and 5206.3 pg/mL, respectively." (PMID 32823758, 2020). "In cancer cells, this interaction facilitates invasion via increased production and activity of MMP-1, -3, -9, and VEGF." (PMID 32630820, 2020). "A receiver operating characteristic curve analysis showed that MMP-1 was effective in separating non-cancer groups from patients with OSCCs at the oral cavity." (PMID 32823758, 2020). "Regarding MMP-1, there are studies in the literature correlating its circulating levels with forms of cancer." (PMID 32425999, 2020).
cancer (continued). "Marimastat inhibits MMP-2, MMP-9, MMP-1, and other MMPs and, it has been reported to inhibit cancer cell migration 3D in vitro at a 30 μM concentration and to inhibit fibroblast mediated collagen hydrogel contraction at a 10 μM concentration." (PMID 32384738, 2020). "MMP1 was identified as a promising cancer driver gene related to the transformation from healthy cells to IPF, and from healthy cells to NSCLC." (PMID 33046043, 2020). "The high levels of MMP1 released by metastatic cells disrupt the inter-endothelial junctions to promote transmigration of cancer cells through the brain endothelium." (PMID 33002044, 2020). "Zn level was not considered in previous studies investigating association of MMP-1, MMP-2, MMP-7, MMP-13 and MT2A polymorphism with cancer risk." (PMID 32765800, 2020). "As mentioned, upregulated expression of MMP-1 in tissue, serum, and/or urine specimens has been reported in several other cancer types." (PMID 32823758, 2020). "Multiple GO terms were enriched associated with MMP-1, MMP-2, MMP-9 and VEGF, and they are closely associated with pathways, proteoglycans and microRNAs related to cancer." (PMID 31311559, 2019). "As one of the main component in the extracellular matrix of skin tissue, collagen was usually degraded by MMP1/3 under inflammatory or cancer microenvironment." (PMID 31761787, 2019). "For these in vitro experiments, HT-1080 cancer cell spheroids were electroporated with a control siRNA, MMP-1 and MMP-2 siRNAs, or MT1 siRNA." (PMID 30903592, 2019). "Our present data of an interconnections between OPN and other proteases such as MMP-1, −2, −3, −7, −12, and uPA, in normal human breast tissue are in line with previous studies of several cancer forms." (PMID 31475105, 2019). "MMP1 is a critical collagenase regulating cancer cells migration and metastasis and its major substrates are collagens I, II and III." (PMID 30379883, 2018). "In recent studies, the G-protein-coupled receptor PAR1 has been found to be cleaved and activated by MMP-1, which promotes cancer cell migration and invasion." (PMID 30026761, 2018). "Overexpression of matrix metalloproteinase 1 (MMP1) by cancer cells in OSCC is essential for the process of EMT." (PMID 30248985, 2018). "Integrin α2β1 was shown to regulate several cancer progression related genes, most notably matrix metalloproteinase-1 (MMP-1), a recognized invasion promoting protein." (PMID 30197754, 2018). "Assessment of MMP1, 2, and 9 in the cells showed that Nischarin positive cancer cells have a reduction in expression of all three MMPs." (PMID 29415725, 2018). "A trend towards increased marker levels was observed with cancer progression, particularly for MMP-1 and MMP-9." (PMID 29207990, 2017). "Overall, our findings clearly demonstrate that high-metastatic cancer cells secreted EVs carrying MMP1 mRNAs, which effectively damaged mesothelial cells, promoting peritoneal dissemination." (PMID 28262727, 2017). "We then used Oncomine database to elucidate MMP1 mRNA expression in different types of cancers and different subtypes of BC." (PMID 29207651, 2017). "The established role of MMP-1 in cancer intravasation, coupled with our findings that MLK3 controls MMP-1 levels, prompted us to evaluate the components of the MLK3–FRA-1–MMP-1 signaling axis in CTCs." (PMID 28604765, 2017). "Another recent study reported that PITPNC1 drives metastasis of multiple prevalent cancer types by enhancing Rab1B-mediated vesicular secretion of several pro-metastatic genes, which include MMP1." (PMID 28316326, 2017). "First, high MMP1 expressions at both mRNA and protein levels were found in BC cancer tissues compared with corresponding normal samples." (PMID 29207651, 2017). "Whole transcriptome analysis shows that MMP1 is significantly elevated in mesothelial cells treated with highly metastatic cancer EVs and intact MMP1 mRNAs are selectively packaged in the EVs." (PMID 28262727, 2017).